CRP (C-reactive protein)
Diseases named in the same sentence as CRP in open-access papers (continued):
Sharing a sentence is not in itself a finding about the gene and the disease.
colitis (104 papers, 2011 to 2025). Inflammation of the colon. "This study demonstrated that the damage related to colitis was associated with a significant increased levels of CRP and MPO activities in the colon." (PMID 40359212, 2025). "Fecal calprotectin (FC) has good diagnostic sensitivity and is significantly associated with C-reactive protein (CRP) in patients with colitis." (PMID 36873123, 2023). "Anderson and Rapport recently suggested a biomarker profile incorporating IL-17/IFN-γ/IL-10/TGF-β1/CRP based on findings from ipilimumab-associated colitis." (PMID 31293970, 2019). "For example, inhibition of PARP dampens inflammation associated with colitis, while elevated levels of CRP and S100A8, for example, have been associated with inflammatory pathologies." (PMID 30814064, 2019). "In the case of CRP, IL-6, IL-12, and IL-10, the addition of both beta-glucans to the feed of animals with induced colitis caused a statistically significant reduction of their level to the level observed in healthy control group (HβG−) or even lower." (PMID 31590413, 2019). "In contrast, poor outcomes and increased risk of irAE recurrence have been associated with high-grade CIP, initial irAE of colitis or hepatitis, advanced age, and elevated levels of IL-6, CRP, WBC, and absolute neutrophil count (ANC) at the time of rechallenge." (PMID 40984918, 2025). "We previously reported that CRP, as a systemic inflammatory marker, was associated with the disease extension, and the cut-off for ER had the tendency to increase from rectal (E1) to extensive colitis (E3)." (PMID 39451607, 2024). "Moreover, the severity of colitis is associated with higher levels of serum CRP, which is a biomarker of colon inflammation." (PMID 35745756, 2022). "The “clinical” progression of colitis was also confirmed by quantifying neutrophil infiltration in the lamina propria, according to the Nancy histological score, by measuring weight loss, serum IL-6, CRP, and Lipopolysaccharide (LPS)." (PMID 33431850, 2021). "However, administration of 17β-estradiol or G-1, a selective GPER agonist, reduced GPER expression at the mRNA and protein level and was associated with improved colitis scores as well as CRP protein level." (PMID 31261736, 2019). "Moreover, there was an associated significant reduction in inflammatory markers of colitis: both C-reactive protein (CRP) and fecal calprotectin." (PMID 31067701, 2019). "Interestingly, the damage associated with colitis resulted in a significant elevation of serum levels of CRP and MPO activity in the colon, while these elevated levels were notably reduced in those rats that received MSPNP treatment, which exerted their protective role against colon damage." (PMID 35745756, 2022). "CRP showed fair inter-rater agreement with the Patient Simple Clinical Colitis Activity Index (P-SCCAI) and the SCCAI, while a substantial agreement was found between the Physician Global Assessment (PGA) and both P-SCCAI and SCCAI." (PMID 40795293, 2025). "European Crohn ́s and Colitis Organisation-European Society of Gastrointestinal and Abdominal Radiology guidelines indicate fecal calprotectin (FC) and C-reactive protein (CRP) as useful biomarkers in the management of IBD." (PMID 39292974, 2025). "Our case highlights a discordance in these indicators and demonstrates C-reactive protein as an important marker in assessing residual colitis and disease resolution." (PMID 40502301, 2025). "Patients with active proctitis and active extensive colitis were compared regarding their CRP and FCP values." (PMID 39451607, 2024). "Since colitis is a systemic inflammatory disease, in addition to colonic tissues, we also examined serum levels of cytokine and C-reactive protein (CRP)." (PMID 38380090, 2024). "In this prospective study, CRP levels were significantly higher in patients with active extensive colitis than those with active proctitis." (PMID 39451607, 2024).
colitis (continued). "The difference between the CRP values of patients with proctitis and extensive colitis was significant (p = 0.04)." (PMID 39451607, 2024). "In the extensive colitis group, the median CRP was 12 mg/L (IQR: 15.3), and the median FCP was 831 μg/g (IQR: 990)." (PMID 39451607, 2024). "Current guidelines consider predominantly CTCAE grade of reported diarrhea and colitis symptoms for clinical management; thus, their correlation with CRP is relevant for initial evaluation of IMDC severity." (PMID 37476185, 2023). "We found higher CRP level was associated with higher CTCAE grade of clinical symptoms such as diarrhea (p=0.015), colitis (p=0.013), and endoscopic findings (p=0.016)." (PMID 37476185, 2023). "The findings of this study demonstrate that AEUD improves colonic inflammation and oxidative stress in DSS-induced colitis by decreasing CRP levels, promoting the main antioxidant enzyme activities, and reducing colonic lipid peroxidation and H2O2 levels." (PMID 38004039, 2023). "Pre-emptive exclusion of infectious diseases and blood testing (blood count, CRP, celiac disease serology, metabolic panel, electrolyte levels, etc.)are important to assess the colitis’ etiology and severity." (PMID 37511260, 2023). "This study showed that in colitis patients, there was a significant correlation between FC and CRP levels, even after adjusting for age." (PMID 36873123, 2023). "There was a significant correlation between endocan and CRP in the patient group (r2 = 0.78), and also there was a significant correlation between endocan and CRP in patients with extensive colitis (r2 = 0.54)." (PMID 37041496, 2023). "The POCER study on 86 asymptomatic colitis patients analyzed the relationship between FC and CRP levels with the severity of postoperative endoscopic recurrence." (PMID 36873123, 2023). "It has been shown that feeding colitis rats β-glucans-rich oatmeal reduced the high levels of c-reactive protein (CRP), Interleukin-12 (IL-12), and Interleukin-6 (IL-6) in the walls of the colons after only seven days." (PMID 36769034, 2023). "According to the literature, a minimum of two biomarkers, including FC and CRP, are required to establish a diagnosis of colitis in a patient." (PMID 36873123, 2023). "Assessing the levels of FC and CRP among patients with colitis can be useful to assess the worsening of symptoms early and reduce mortality and morbidity." (PMID 36873123, 2023). "This analytical study with a cross-sectional design was conducted to evaluate the activity of colitis using the results of C-reactive protein (CRP) and fecal calprotectin (FC) assays." (PMID 36873123, 2023). "The area under curve (AUC) of CRP + D-D + α2-MG for predicting distal colitis MES3 was 0.85, and the AUC of IL-6+ GSP+ α1-MG predicted extensive colitis MES3 can reach 0.82." (PMID 37457023, 2023). "-Complete number of tender and swollen joints;-Spine examination;-X-ray or US joint examination;-Blood panel including RF, anti-CCP, ESR, and CRP;-Consider MRI of affected joints and tendons;-Blood panel including HLA-B27;-Endoscopy when colitis suspected." (PMID 36981837, 2023). "The median baseline CRP levels were 17.1 mg/L in patients with grade 1 colitis and 49.0 mg/L in patients with grade 2-4 colitis (p=0.013)." (PMID 37476185, 2023). "This study demonstrated that FC had a significant relationship with CRP (r=0.57; p<0.001) in patients with colitis." (PMID 36873123, 2023). "The treatment time impacted the levels of C-reactive protein, with a higher dosage being observed with a 5-day treatment for all groups that had colitis induction (p < 0.05)." (PMID 37898635, 2023). "Especially in patients with extensive colitis, hs-CRP and CAR are closely related to EA and show a higher diagnostic value compared to the related CBC parameters." (PMID 36572872, 2022). "Herein, induction of colitis by DSS evoked an elevated CRP levels in serum when compared to the control non induced group." (PMID 35332200, 2022).
colitis (continued). "Meanwhile, BANPs treatment reduced CRP levels in the serum reflecting their positive therapeutic effect on colitis." (PMID 35332200, 2022). "Valsartan and sulfasalazine treatment was associated with a lower reduction in colon length, diminished colon weight, and high sensitivity C-reactive protein level in mice with DSS-induced colitis." (PMID 33628160, 2021). "Feeding colitis rats with feed containing oat beta-glucans led to a reduction of high levels of CRP, Il-6, and Il-12 in the colon wall after 7 days." (PMID 33923129, 2021). "The effects of hydrogen treatment alone or in combination with sulfasalazine on high-sensitive C reactive protein (hs-CRP) levels were also evaluated in DSS-induced colitis." (PMID 34345230, 2021). "Although CD and UC are both inflammatory diseases, CRP is a less reliable marker of inflammation and disease activity in patients with UC, perhaps except for severe, extensive colitis." (PMID 33139618, 2020). "Further work is needed to determine if monitoring the change in CRP is useful during treatment of severe irAE colitis." (PMID 32418993, 2020). "These natural compounds significantly reduced the values of specific serum oxidative and proinflammatory markers (superoxide dismutase, myeloperoxidase, malondialdehyde, prostaglandin E2, TNF-α, IL-β, and C-reactive protein) in TNBS -induced colitis." (PMID 32867139, 2020). "The performance of other markers (hemoglobin, CRP, orosomucoid, erythrocyte sedimentation rate, albumins) or the Simple Clinical Colitis Activity Index (SCCAI) as predictors of deep remission and inflammatory activity was not accurate." (PMID 32498475, 2020). "There was a significant difference between IFN-γ level and severity of colitis, and patients with elevated C-reactive protein had a trend for higher IFN-γ mRNA levels." (PMID 32811425, 2020). "C-reactive protein (CRP) level and IL-6 were observed to reflect the clinical course of colitis clearly, which exposed the potentiality nivolumab-related toxicities predictive value." (PMID 33123120, 2020). "In our results, we demonstrated that repeated EA intervention ameliorates DSS-induced colitis by suppressing proinflammatory mediators, including CRP, IFN-γ, TNF-α, and IL-6 through the TLR4 signaling via MyD88-dependent pathway." (PMID 32419794, 2020). "High APACHE II score reflected that the patients were sicker and more vulnerable to severe forms of CDI while high CRP was consistent with the severity of colitis." (PMID 31530847, 2019). "A particularly important outcome of the study is that now it can be presumed that the level of urinary aMT6s excretion can serve as a biomarker and activity index of colon inflammation in patients with UC, along with C-reactive protein and fecal calprotectin." (PMID 29382152, 2018). "Characteristics including left-sided colitis/proctitis, fCal ≤250 μg/g, C-reactive protein [CRP] ≤6 mg/L, baseline MMS, endoscopic subscore (ES) = 2, SF subscore <3, and no prior biologic or tofacitinib failure were significantly associated with DC at W12 in the univariable analysis." (PMID 40651005, 2025). "Furthermore, colitis severity is accompanying higher levels of CRP, common pro-inflammatory agent, which is a biomarker of colon inflammation." (PMID 40359212, 2025). "However, CRP levels remained elevated at 88 mg/L, reflecting persistent residual colitis, which was confirmed by colonoscopy." (PMID 40502301, 2025). "An effective serum biomarker other than the routine measurement of patients’ C-reactive protein (CRP) is thus desired as a diagnostic tool to predict the presence or absence of IBD or other forms of colitis in outpatient clinics at individuals’ initial visits." (PMID 38792498, 2024).
colitis (continued). "We were inspired by a previous study, in which CRP levels ≥10 mg/L or a clinical score ≥5 (the Harvey–Bradshaw index for CD and the Simple Clinical Colitis Activity Index for UC) predicted a nearly fourfold increased risk of steroid therapy or surgery after the 14-week induction therapy period." (PMID 38398240, 2024). "Additionally, it has been suggested that in UC, fecal calprotectin level has a better significance for detecting colitis compared to CRP." (PMID 38983722, 2024). "FC levels have a better significance for detecting colitis compared to CRP." (PMID 36873123, 2023). "In patients with extensive colitis, the AUC of CRP, FC, IL-6, FDP, GSP and α1-MG independently predicted MES 3 is 0.70, 0.65, 0.70, 0.73, 0.76, and 0.70, respectively, and the AUC of IL-6 + GSP+ α1-MG predicted MES3 can reach 0.82, with sensitivity and specificity of 66% and 94%, respectively." (PMID 37457023, 2023). "Vitamin D can also be connected with inflammatory markers of colitis: CRP and fecal calprotectin." (PMID 33809912, 2021). "Considering clinical characteristics, some studies have demonstrated that, in CD patients, young age, isolated colitis, and elevated CRP levels are predictors of response to anti-TNF therapy, while smoking and disease duration more than 2 years are predictors of non-responders." (PMID 31316377, 2019). "DSS treatment of SIV-infected African green monkeys, a natural host species for SIV that does not manifest GI tract damage or chronic immune activation during infection, results in colitis with elevated levels of plasma SIV RNA, sCD14, LPS, CRP and mucosal CD4+ T-cell loss." (PMID 26282376, 2015). "Moreover, we found that there was a significant association between CRP value and endoscopic severity at IMDC onset, specifically when active inflammation was present on endoscopy, which serves as the gold standard for objective evidence of colitis." (PMID 37476185, 2023). "Infliximab evidently improved CD patients' symptoms and 1-month treatment alleviated colitis with significant reduction in CDAI and CRP." (PMID 40484317, 2025). "The median CRP and LRG values in the normal-mucosa group were significantly lower than those of the IBD and other IBD-colitis groups, respectively, as follows: CRP, 0.03 mg/dL vs. 0.17–0.45 mg/dL, p < 0.01; LRG, 9.5 μg/mL vs. 13.6–22.1 μg/mL, p < 0.01." (PMID 38792498, 2024). "There was a significant positive correlation between SAA and FC, CRP, NLR, platelet count and the Simple Clinical Colitis Activity Index (SCCAI)." (PMID 38256249, 2024). "Blood tests, including complete blood count, comprehensive metabolic panel, C-reactive protein (CRP), and thyroid-stimulating hormone, are also recommended for noninvasive assessment of ICI-induced colitis." (PMID 38461170, 2024). "CRP and SAA plasma were also compared between treatments, and their level assessments only showed noteworthy results in DSS colitis." (PMID 37047397, 2023). "Our study demonstrated that CRP level at IMDC onset correlates with CTCAE grade of diarrhea and colitis, as well as degree of endoscopic inflammation." (PMID 37476185, 2023). "Regarding the APPs’ correlation to mRNA markers, there were moderate positive correlations between CRP levels and Il6, Hif1a, and Il1b1 expression in both trials with DSS-induced colitis." (PMID 37047397, 2023). "Additional, serum C-reactive protein (CRP) and leucine-rich alpha 2 glycoprotein (LRG) were significantly increased in DSS-induced colitis mice." (PMID 35269806, 2022). "Additional, serum CRP and LRG were significantly reduced in DSS-induced colitis mice treated with corylin." (PMID 35269806, 2022). "In active colitis there is an increase in White Blood Cells (WBC), C-Reactive Protein (CRP) and Erythrocyte Sedimentation Rate (ESR), reflecting the inflammatory condition." (PMID 36676712, 2022).
colitis (continued). "Simple clinical colitis activity index (SCCAI), fecal calprotectin (FC), C-reactive protein (CRP), Erythrocyte Sedimentation Rate (ESR), and Sf-36 questionnaire have been used for assessment at the baseline and the end of the trial." (PMID 34567156, 2021). "All patients had elevated serum C-reactive protein (CRP) and fecal calprotectin (FCP) levels at study entry indicating systemic and colonic inflammation, respectively." (PMID 33921143, 2021). "In the present study, it was observed that the levels of CRP, IFN-γ, TNF-α, and IL-6 were elevated in mice plasma with DSS-induced colitis." (PMID 32419794, 2020). "The proportion of patients with total colitis, rate of hospitalization, cytomegalovirus (CMV) infection, pMS, MES, and baseline CRP level tended to be higher in the TAC group." (PMID 32719413, 2020). "C-reactive protein (C-rp), TNF-α, and NF-κB levels decreased with an improvement of clinical colitis activity index score." (PMID 31906123, 2019). "In a colitis mouse model, intra-rectal injections with CST resulted in decreased serum levels of the acute phase reactant C-reactive protein (CRP) and suppressed activity of myeloperoxidase (MPO), which is a marker for granulocyte infiltration." (PMID 30337922, 2018). "At the development of colitis, all reported cases had a long-term disease duration, high BASDAI, elevated ESR/CRP levels and advanced joint involvement refractory to the usage of NSAIDs and salazopyrin." (PMID 29030592, 2017). "The marked suppression of TNF-α and CRP in the HDP group is consistent with findings in rodent models, where postbiotics downregulated NF-κB signaling and mitigated cytokine storms in inflammatory conditions such as colitis." (PMID 41209733, 2025). "Additionally, PPE can alleviate inflammatory symptoms of colitis and reduced serum levels of the inflammatory markers (TNF-α, IL-6, and CRP) owing to its anti-inflammatory properties." (PMID 40359212, 2025). "Thirdly, inflammatory markers, such as ESR and CRP, were not ordered consistently enough to provide more support in diagnosing colitis." (PMID 41180291, 2025). "In our study, we found that the inflammatory markers (FC, ESR, and CRP) were significantly higher in patients with MC than those without colitis." (PMID 39451656, 2024). "Patients with MC had significantly higher FC, ESR, and CRP levels than those without colitis (p < 0.001)." (PMID 39451656, 2024). "Expression of CRP, ESR, FC and cytokines in distal and extensive colitis." (PMID 37457023, 2023). "The expression of CRP, ESR, FC, interleukin-6(IL-6), IL-8 and IL-10 were different between the two groups, and except for IL-4 and IL-12P70, the expression of inflammatory markers was higher in extensive colitis." (PMID 37457023, 2023). "In colitis animals, co-administration of ARP and CRP at precise levels might ameliorate clinical symptoms, restore immunological balance, and reduce colonic mucosal damage." (PMID 35860025, 2022). "In this study, we observed that HZJDD remarkably reduced the level of IL-6, CRP, and TNF-α in DSS-induced colitis rats, indicating that HZJDD could exert anti-inflammatory effects against DSS-induced in UC rats." (PMID 36313293, 2022). "Inflammation in the colon (colitis) was confirmed in the same animals not only histologically but also biochemically, including analysis of colon level of pro-inflammatory cytokines (i.e., Il-1; Il-6 or TNF alfa) and CRP protein." (PMID 33499397, 2021). "Inflammatory markers, including C-reactive protein (CRP), lymphotactin, monocyte chemoattractant protein-5, and macrophage inflammatory protein-2, were increased in the serum of mice with TNBS-induced colitis compared with untreated mice." (PMID 32332834, 2020). "Diagnostic work-up for colitis includes standard laboratory testing to assess for infectious vs. non-infectious etiologies including CBC, CMP, ESR, and CRP." (PMID 31293970, 2019).